SORBS2 (sorbin and SH3 domain containing 2)
Diseases named in the same sentence as SORBS2 in open-access papers (continued):
Sharing a sentence is not in itself a finding about the gene and the disease.
tumor (33 papers, 2009 to 2026). "SORBS2 was significantly downregulated in metastatic tissues and positively associated with overall survival and tumor grade." (PMID 33311452, 2020). "In addition, SORBS2 functions as a potential tumor suppressor in cervical carcinogenesis, and loss of SORBS2 function in mice leads to impaired dendritic development and memory." (PMID 33410284, 2021). "single-cell RNA analysis revealed that myofibroblasts are the predominant cellular source of SORBS2 expression within ESCC tumor tissue." (PMID 41766902, 2026). "By sustaining SORBS2 expression through chromatin looping, LINC02454 makes tumor cells more susceptible to TMZ-induced cytotoxicity." (PMID 41154382, 2025). "SORBS2 is an RNA-binding protein that plays a crucial role in suppressing the metastatic colonization of cancers by stabilizing tumor-suppressive transcripts." (PMID 40330466, 2025). "Sorbin and SH3 domain-containing 2 (SORBS2) function as a tumor suppressor and is characterized by significantly diminished expression levels in HCC." (PMID 40275278, 2025). "By stabilizing these transcripts, SORBS2 enhances their expression, thereby limiting the invasiveness of cancer cells and promoting a tumor-suppressive immune microenvironment." (PMID 40330466, 2025). "Mechanistically, SORBS2 protein stabilizes mRNAs with tumor suppressor function by binding to their 3′UTR." (PMID 38177123, 2024). "SORBS2 suppresses metastatic colonization of OC by stabilizing tumor-suppressive immunomodulatory transcripts." (PMID 37632669, 2024). "Using qRT-PCR, we also verified that the gene AS events SORBS2 were downregulated in tumor tissue, and gene AS events EPB41L2, CELF2, TMEM130, and VCL were upregulated in tumor tissue." (PMID 34692669, 2021). "We further examined the hub gene AS events and hub gene mRNA expression between five paired normal and tumor tissues by qRT-PCR, and found that the PSI of EPB41L2, TMEM130, and SORBS2 were different from tumor to normal." (PMID 34692669, 2021). "Expect for SORBS2, all of the other four genes were differentially expressed between tumor and normal tissues." (PMID 33934539, 2021). "Analysis of 50 pairs of normal and HCC tissues in the TCGA‐LIHC dataset revealed that except for SORBS2, the four genes were differentially expressed between tumor and normal tissues." (PMID 33934539, 2021). "Our data illustrate a novel post-transcriptional network that links cancer progression and immunomodulation within the tumor microenvironment through SORBS2-mediated transcript stabilization." (PMID 29548303, 2018). "The expression patterns of 6 randomly selected genes in tumor tissues detected by RT-PCR, except SORBS2, were fully consistent with those from the cDNA microarray results." (PMID 24551190, 2014). "SORBS2 is a tumor-suppressor gene predominantly expressed in myofibroblasts." (PMID 41766902, 2026). "Thus, SORBS2 contributes to ovarian cancer suppression by linking tumor progression and immune regulation through its post-transcriptional stabilization of key immunomodulatory transcripts." (PMID 40330466, 2025). "SEC61A2 may be important for metastasis to the brain in humans when upregulated and finally SORBS2 has been reported to be a tumor suppressor gene in ccRCC." (PMID 35954157, 2022). "Here we identified the RBP SORBS2 as a tumor suppressor in ccRCC." (PMID 33311452, 2020). "The TCGA data revealed that repressed SORBS2 expression was correlated with higher tumor grade." (PMID 33311452, 2020). "Moreover, SORBS2 silencing significantly shortened survival of tumor-bearing mice compared with the control group." (PMID 29548303, 2018). "In line with a functional involvement of alternatively activated myeloid cells in influencing tumor burden, the number of CD11b + GR1+ myeloid infiltrates within the tumor tissue of the SORBS2-knockdown group were significantly increased compared with those in the control ID-8 group." (PMID 29548303, 2018).
tumor (continued). "Therefore, SORBS2 depletion-induced secretome alterations are associated with monocyte to MDSC and M2-like macrophage polarization, which indicates an immunomodulatory role of SORBS2 and its stabilized transcripts in the tumor microenvironment." (PMID 29548303, 2018). "In contrast, patients with insufficient expression of SORBS2, PAM, ZFAT, DOCK7, ERMAP, BTF3, and GUSB in the tumor tissues had shorter survival duration than patients in the high-expression group." (PMID 37315301, 2023). "Sorbin and SH3 domain-containing 2 (SORBS2), an RBP, has been reported to be a potent tumor suppressor in several cancer types." (PMID 33311452, 2020). "Significant genetic losses were assumed to contain potential tumour-suppressor genes: DPYD (1p21.3); CLDN22, CLDN24, ING2, CASP3, SORBS2 (4q34.2-q35.1); DEFB (8p23.1)." (PMID 26019623, 2015). "Finally, recent investigations have shown RBP sorbin and SH3 domain-containing (SORBS) proteins, including SORBS1, SORBS2 and SORBS3, exhibit tumor suppressive function in cancer growth." (PMID 37038184, 2023).
cancer (20 papers, 2009 to 2026). A tumor composed of atypical neoplastic, often pleomorphic cells that invade other tissues. "Another potentially important gene dysregulated in HPV-associated cancers is SORBS2, which was revealed by microarray analysis to be downregulated in cervical premalignant lesions and HNSCCs." (PMID 36145459, 2022). "The expression of SORBS2 suppresses the metastasis of a number of cancers, and its ectopic expression in cells in vitro results in a significant reduction in anchorage-independent growth and colony formation." (PMID 36145459, 2022). "Specifically, we focused on the pro-cancer immunomodulatory role of SORBS2 and its bound targets WFDC1 and IL-17D." (PMID 29548303, 2018). "Enhanced expression of either WFDC1 or IL-17D potently represses SORBS2 depletion-mediated cancer metastasis promotion." (PMID 29548303, 2018). "Our analysis revealed 9 shared genes, with UBE2C, POLQ, RAD51, and HOXB7 being up-regulated and EDNRB, GPD1L, F10, SORBS2, and CXCL12 down-regulated in both cancers." (PMID 41790655, 2026). "Top up-regulated genes related to cancer were: (i) IL-20, CLK1, SORBS2, ERG1, PIM1, SNORD3A for normal FHC cells and (ii) TSLP, BHLHA15, LAMP3, ZNF27B, KRT17, ATF3 for cancerous HT29 cells." (PMID 38033043, 2023). "All the most up-regulated genes (IL-20, CLK1, SORBS2, ERG1, PIM1, SNORD3A) are involved in cancer development." (PMID 38033043, 2023). "The 6 up-regulated genes (IL-20, CLK1, SORBS2, ERG1, PIM1, SNORD3A) are involved in cancer development." (PMID 38033043, 2023). "The other three genes that showed consistent expression across all models, SORBS2, RGS12, and EXOC6, have been investigated as predictive or prognostic cancer biomarkers." (PMID 28798985, 2017). "Other genes down-regulated by rosiglitazone belonged mainly to two functional groups: “cancer” (RPS27A, SORBS2, STIP1, FGA, FGFR2, SSH3, EPN1) and cell death (SORBS2, STIP1, GAS2, EPN1)." (PMID 22761953, 2012). "The smallest region of overlap (region 4q35.1-4q35.2) encompasses the cancer associated genes TLR3, CDKN2AIP, ING2, CASP3 and SORBS2, none of which are thought to cause aberrant DNA methylation." (PMID 20444249, 2010).
cardiovascular diseases (1 paper, 2022). "When we included previously diagnosed cardiovascular diseases in the EWAS regression model as a covariate, associations between treatment response and methylation of the DMR in SORBS2 remained significant." (PMID 35794104, 2022). "Also, in a separate analysis, previously diagnosed cardiovascular diseases did not predict methylation in SORBS2 (all p > 0.46)." (PMID 35794104, 2022).
infection (1 paper, 2021). The state of being infected such as from the introduction of a foreign agent such as serum, vaccine, antigenic substance or organism. "For instance, the protein SORBS2 is always over-expressed during the infection, compared to non-infected cells, but a peak in protein abundance up to 7.5-fold is observed at 72 hpi when the bacterium is actively replicating." (PMID 34073568, 2021).
metabolic disease (1 paper, 2022). A congenital disorder (due to inherited enzyme abnormality) or acquired (due to failure of a metabolically important organ) disorder resulting from an abnormal metabolic process. "Genetic Variation in SORBS2 has repeatedly been associated with cardiovascular and metabolic diseases." (PMID 35794104, 2022).
SORBS2 also shares sentences with these, for which no sentence is quoted: diabetic nephropathy (2 papers); bladder cancer (1); breast carcinoma (1); Calcium nephrolithiasis (1); colorectal cancer (1); familial adult myoclonic epilepsy (1); genetic disease (1); idiopathic cardiomyopathies (1); Intellectual disability (1); Left ventricular noncompaction cardiomyopathy (1); lymph node metastases (1); neurological diseases (1); peripheral nerve injury (1); renal carcinoma (1); Renal Cell Cancer (1); retinitis pigmentosa 23 (1); spinal cord injury (1); Tinnitus (1).